CXCL16 (C-X-C motif chemokine ligand 16)
Diseases named in the same sentence as CXCL16 in open-access papers (continued):
Sharing a sentence is not in itself a finding about the gene and the disease.
nephrotic syndrome (3 papers, 2014 to 2016). A collection of symptoms that include severe edema, proteinuria, and hypoalbuminemia; it is indicative of renal dysfunction. "The involvement of NF-kappaB p65 in renal failure may be due to its interaction with inflammatory chemokines, such as CXCL16, which was increased in active nephrotic syndrome patients and correlated with blood lipids, urine protein and inflammation responses." (PMID 24997640, 2014). "Serum CXCL16 was increased in patients with active NS and correlated with blood lipids, urine protein and immune and inflammation responses, suggesting that CXCL16 may serve as a useful index or biomarker for disease activity in children with nephrotic syndrome." (PMID 24460887, 2014). "In summary, we found that serum CXCL16 is increased in patients with active NS and is correlated with blood lipids, 24-hour urine protein and immune and inflammation responses, suggesting that CXCL16 may serve as a useful index or biomarker for disease activity in children with nephrotic syndrome." (PMID 24460887, 2014).
neuroblastoma (3 papers, 2014 to 2021). Neuroblastoma (NB) is the most common solid, extracranial childhood tumor. "Conversely, CXCL16 gene expression of murine neuroblastoma N2A cells and cortical astrocytes treated with universal IFN-α remained unchanged." (PMID 34804996, 2021). "We found significant up-regulation of mRNA and protein expression of CXCL16 in C282Y-HFE neuroblastoma cells." (PMID 24533143, 2014). "All IFN-α-treated human CNS cell lines, comprising human neuroblastoma cells (SK-N-SH), human microglia-like cells (HMC3), and human astrocyte-like cells (SVGp12), showed a downregulation of CXCL16 gene expression upon RABV Tha strain infection in contrast to the IFN-α-treated mock." (PMID 34804996, 2021).
renal cell carcinoma (3 papers, 2021 to 2025). "However, in some types of cancer cells, expression of CXCL16 is often downregulated, e.g., by promoter methylation in renal cell carcinoma cells." (PMID 33800554, 2021). "Interestingly, CXCL16 may also reduce the proliferation of cancer cells, which was shown in renal cell carcinoma cells." (PMID 33800554, 2021).
soft tissue sarcoma (3 papers, 2014 to 2025). A malignant neoplasm arising from muscle tissue, adipose tissue, blood vessels, fibrous tissue, or other supportive tissues excluding the bones. "Similarly, glycolytic CAFs (glyCAFs) in soft tissue sarcomas create an immunosuppressive niche by producing CXCL16, which establishes a physical and chemotactic barrier to CD8+ T cell infiltration." (PMID 40940809, 2025).
systemic sclerosis (3 papers, 2011 to 2022). A chronic disorder, possibly autoimmune, marked by excessive production of collagen which results in hardening and thickening of body tissues. "A previous study reported that CXCL16 was elevated in the systemic sclerosis (SSc) serum from the patients with pulmonary arterial hypertension." (PMID 36246557, 2022).
type 1 diabetes (3 papers, 2017 to 2024). "What′s more, RES has a protective effect on pancreatic β-cells in type I diabetes, potentially reducing β-cell expression by modulating the CXCL16/oxidized low density lipoprotein pathway." (PMID 38933889, 2024). "Studies have shown that RES can suppress the expression of islet CXC chemokine ligand 16 (CXCL16) and the NF-κВ p65 in type I diabetes." (PMID 38933889, 2024).
acute pancreatitis (2 papers, 2018 to 2024). An acute inflammatory process that leads to necrosis of the pancreatic parenchyma. "Taken together, these studies employing Cxcl16-deficient mice strongly suggest that induction of Cxcl16 expression at a late phase of acute pancreatitis promotes the development of acinar cell necrosis through migration of myeloid cells into the inflamed pancreas." (PMID 29891873, 2018). "A cytokine/chemokine array using sera from patients with acute pancreatitis (AP) revealed that serum CXCL16 levels were elevated according to the severity of pancreatitis." (PMID 29891873, 2018). "Therefore, Cxcl16 expression, which is induced at a late phase of acute pancreatitis on day 2, leads to the development of acinar cell necrosis through recruitment of myeloid cells into the pancreas." (PMID 29891873, 2018). "We also demonstrated that Cxcl16 could be a potential therapeutic target for acute pancreatitis." (PMID 29891873, 2018). "Thus, CXCL16 was considered to be a candidate chemokine that determines the severity of pancreatitis since its expression was markedly up-regulated only in the late phase of acute pancreatitis with acinar cell necrosis." (PMID 29891873, 2018).
Alzheimer disease (2 papers, 2023). A progressive, neurodegenerative disease characterized by loss of function and death of nerve cells in several areas of the brain leading to loss of cognitive function such as memory and language. "This study reported that CXCL16/CXCR6 crosstalk between microglia and T cells restricted Alzheimer’s disease pathology due to their immunosuppressant activity." (PMID 38005878, 2023). "Another recent study found that CXCL16/CXCR6 signaling orchestrated the retention of resident memory T cells within the brains of human Alzheimer’s disease patients and mouse models of Alzheimer’s disease." (PMID 38005878, 2023).
atopic dermatitis (2 papers, 2014 to 2021). "A number of chemokines [CCL2, CCL3, CLL4, CCL8, CCL13, CCL19, chemokine (C-X-C motif) ligand (CXCL) 1, CXCL6, CXCL16] were upregulated in sensitized dogs after allergen challenge, similar to what is observed in human atopic dermatitis." (PMID 25098772, 2014). "Both these receptors and their ligands, CXCL16 and CCL20 are reported to be overexpressed in atopic dermatitis and lesional psoriatic skin, and contribute to the skin inflammation." (PMID 34162906, 2021).
bladder cancer (2 papers, 2017 to 2021). "For example, the disintegrin and metalloproteinase 10 (ADAM 10) has been shown to regulate the cleavage and shedding of CXCL16, and it was also demonstrated that ADAM 10 regulates the proliferation, invasion and chemoresistance of bladder cancer cells." (PMID 29285224, 2017). "Based on all these information, we checked the expression of CXCL16, T cell chemoattractant in bladder cancer cell lines and identified a significant negative correlation with FGFR1 expression." (PMID 35068946, 2021).
brain injuries (2 papers, 2020 to 2021). "As a consequence, the authors suggest the use of CXCL16 as a potential drug candidate for traumatic brain injuries." (PMID 34804996, 2021).
CADASIL (2 papers, 2023 to 2025). "Previous studies have detected systemic inflammatory cytokines, including IL-1β, IL-6, TNF-α, CCL2, and CXCL16, and found that their expression levels were significantly elevated in CADASIL patients, which is consistent with our results." (PMID 41000387, 2025). "The serum inflammatory cytokines were analyzed by ELISAs and revealed that the levels of serum IL-1β, IL-6, TNF-α, CCL2, and CXCL16 were significantly elevated in the patient group compared with their family members, suggesting a systemic inflammation in CADASIL patients." (PMID 37684694, 2023).
co-infection (2 papers, 2015 to 2024). "The regulatory chemokines CXCL1 and CXCL16 were also increased by infection with Em though concentrations appeared to be increased more dramatically by co-infection." (PMID 39229265, 2024). "In addition, co-infection significantly regulated the mRNA expression of several chemokine and chemokine receptor genes, including CCL3 (1.62-fold), CX3CL1 (1.7-fold), CXCL16 (0.56-fold), CCR1 (2.23-fold), and CXCR4 (1.55-fold)." (PMID 25906258, 2015).
diabetic retinopathy (2 papers, 2020 to 2024). "Since we demonstrated that HRMEC express CXCR6, both by Western blot analysis and immunocytochemistry (data not shown), we next investigated how the CXCL16/CXCR6 axis could be involved in the development of diabetic retinopathy." (PMID 33552057, 2020).
endometriosis (2 papers, 2013 to 2023). The growth of functional endometrial tissue in anatomic sites outside the uterine body. "That meant CXCL16 was associated with progression of endometriosis." (PMID 37393391, 2023). "For example, one study showed that CXCL16 expression was found to increase in endometriosis compared to control group." (PMID 37393391, 2023).
experimental autoimmune encephalomyelitis (2 papers, 2013 to 2014). An autoimmune demyelinating disease of the central nervous system that is produced experimentally in animals by the injection of homogenized brain or spinal cord in Freund's adjuvant. "CXCL16 has also been shown to regulate T cell homing to the CNS in experimental autoimmune encephalomyelitis (EAE), and it was recently shown in this model that immature myeloid cells expressing CXCL16 redirect CXCR3 + CXCR6+ and myelin-specific T cells from CNS to lymph nodes." (PMID 24069377, 2013).
fibrosis (2 papers, 2016 to 2024). the formation of excess fibrous connective tissue in an organ or tissue in a reparative or reactive process. "The antioxidative effect of SIM in this fibrosis liver microtissue model is probably induced by KLF2‐NO signalling in LSECs which upregulates the expression of Chemokine (C‐X‐C motif) ligand 16 (CXCL16) on LSECs." (PMID 38984945, 2024).
gout (2 papers, 2014 to 2021). A condition characterized by painful swelling of the joints, which is caused by deposition of urate crystals. "Studies have found that the concentration of CXCL16 is significantly increased in the synovial fluid of patients with gout, and the migration of polymorphonuclear neutrophils in response to CXCL16 has been observed in vitro." (PMID 35116032, 2021). "Recent, our study indicated that serum CXCL16 levels were significantly increased in CKD and gout subjects and were independently associated with a change of renal function." (PMID 24489966, 2014). "Our previous study indicated that serum CXCL16 levels are significantly increased in subjects with CKD and gout and are independently associated with the change of renal function in these subjects." (PMID 24489966, 2014). "Furthermore, our previous studies showed that serum CXCL16 levels are significantly increased in subjects with CKD and gout, and these levels are significantly associated with renal function." (PMID 24489966, 2014).
Hepatitis (2 papers, 2012 to 2014). Inflammation of the liver. "Previous studies confirmed that CXCR6 and secreted soluble CXCL16 might be responsible for inducing chemotactic migration of proinflammatory cells into arthritic joints and sites of liver inflammation." (PMID 24460887, 2014). "VCAM-1 and CXCL16 increased expression led to the recruitment of CXCR6+ cells by the liver, perpetuating the bystander hepatitis." (PMID 23110209, 2012).
Listeria infection (2 papers, 2019 to 2025). "CXCR6 is highly upregulated on T-lymphocytes in the liver during Listeria monocytogenes infection, possibly in response to CXCL16 expressed by liver sinusoidal endothelial cells." (PMID 30899256, 2019). "Animal studies by Heesch and colleagues on Listeria infection and monocytic proliferation confirmed that LSECs induce the recruitment of CD8+ T lymphocytes in the liver by expressing CXC chemokine ligand 16 (CXCL16), which attracts T cells expressing CXC chemokine receptor 6 (CXCR6)." (PMID 40072101, 2025).
macular edema (2 papers, 2023 to 2026). "The baseline aqueous humor levels of Flt-3L, CXCL-16, and endocan-1 were significantly negatively correlated with the change in macular edema in CRVO patients." (PMID 38276038, 2023). "We identified the four novel inflammatory factors as possibly involved in macular edema: FMS-related tyrosine kinase 3 ligand (Flt-3L), fractalkine, CXC chemokine ligand 16 (CXCL-16), and endocan-1." (PMID 38276038, 2023).
malaria (2 papers, 2023 to 2025). Malaria is a serious and sometimes fatal disease caused by a parasite that commonly infects a certain type of mosquito which feeds on humans. "In pregnancy-associated malaria, chemokines such as CXCL-4, CXCL-13, CXCL-16, and CCL-24 play critical roles in leucocyte trafficking to tissue sites in the infected placenta where inflammatory reactions are active." (PMID 36689438, 2023).
pancreatitis (2 papers, 2018 to 2024). Inflammation of the pancreas. "To investigate the causal relationship between the increase in serum CXCL16 levels and the progression of severe pancreatitis, we used a cerulein-induced mouse AP model." (PMID 29891873, 2018). "Notably, only serum CXCL16 levels had significant association with the severity of the pancreatitis and the relation was further confirmed in the validation set." (PMID 29891873, 2018). "Histological examination revealed the development of necrotizing pancreatitis and edematous pancreatitis in mice treated with control Ab and anti-Cxcl16 Ab, respectively." (PMID 29891873, 2018). "Cxcl16−/− mice revealed similar sensitivity as wild-type (WT) mice to the onset of pancreatitis, but better resisted development of acinar cell necrosis with attenuated neutrophil infiltration." (PMID 29891873, 2018). "Such expression pattern of Cxcl16 suggests that Cxcl16 is a molecular switch between edematous pancreatitis and necrotizing pancreatitis." (PMID 29891873, 2018). "Based on an analysis of patient serum samples, mouse pancreatitis models, and in vitro experiments, we found that the chemokine CXCL16 is a key regulator in the development of acinar cell necrosis." (PMID 29891873, 2018). "Among these six candidate cytokines/chemokines, serum CXCL16 level increased in parallel to the severity of pancreatitis whereas such correlation between chemokine levels and the severity of pancreatitis was not seen in the other five chemokines." (PMID 29891873, 2018). "Interestingly, Cxcl16 does not play a role as an acute phase pro-inflammatory mediator in the onset of AP, but rather this chemokine plays a critical role in the late phase of pancreatitis and accelerates inflammatory cascades through the induction of Ccl9 in mice." (PMID 29891873, 2018).
papillary renal cell carcinoma (2 papers, 2017 to 2020). A rare subtype of renal cell carcinoma, arising from the renal tubular epithelium and showing a papillary growth pattern, which typically manifests with hematuria, flank pain, palpable abdominal mass or nonspecific symptoms, such as fatigue, weight loss or fever. "The secretion of IL-8, chemerin, and CXCL16, by papillary renal cell carcinoma, promoted the recruitment of monocytes and the differentiation of macrophages with foam cell phenotype." (PMID 33193674, 2020).
proliferative diabetic retinopathy (2 papers, 2020 to 2022). Advanced retinopathy due to diabetes mellitus characterized by the formation of new vessels in the retina. "Comparisons of vascular endothelial growth factor (VEGF), CXCL16, CX3CL1, ADAM10 and ADAM17 levels in proliferative diabetic retinopathy (PDR) patients with or without active neovascularization and nondiabetic patients with rhegmatogenous retinal detachment (RD)." (PMID 33552057, 2020).
pulmonary arterial hypertension (2 papers, 2011 to 2022). Pulmonary arterial hypertension (PAH) is a group of diseases characterized by mean pulmonary artery pressure >20 mmHg and elevated pulmonary arterial resistance leading to right heart failure. "A previous study reported that plasma CXCL16 concentrations were also significantly increased in patients with IPAH (idiopathic pulmonary hypertension) compared with the control subjects." (PMID 36246557, 2022). "CXCL16 was elevated in SSc serum and increased in SSc patients with early disease, pulmonary arterial hypertension, and those that died during the 36 months of the study." (PMID 21303517, 2011). "Serum CXCL16 was elevated in SSc patients that died between the time of biopsy and the time of data analysis, and in those with pulmonary arterial hypertension and early disease." (PMID 21303517, 2011). "In patients with SSc, CXCL16 was significantly elevated in those with pulmonary arterial hypertension (5.7 ng/ml ± 1.2, n = 2) compared to those without (4.5 ng/ml ± 0.1, n = 18, P < 0.05)." (PMID 21303517, 2011).
rectal cancer (2 papers, 2016 to 2021). A primary or metastatic malignant neoplasm that affects the rectum. "For example, in rectal cancer there is a lower expression of CXCL16 than in normal tissue." (PMID 33800554, 2021). "Research on rectal cancer has shown a decreased expression of CXCL16 in macrophages." (PMID 33800554, 2021).
steatosis (2 papers, 2014 to 2025). Increased lipid within the cytoplasm of cells. "In a mouse model of alcohol-induced liver injury, a Chinese herbal formula that inhibited CXCL16 expression lowered liver enzymes, steatosis, and fibrogenesis, while exogenous CXCL16 administration reversed the improvements, restoring liver injury and fibrosis in the model." (PMID 41373861, 2025). "Importantly, anti-CXCL16 treatment significantly reduced fatty liver degeneration upon MCD diet, as assessed by hepatic triglyceride levels, histological steatosis scoring and quantification of lipid droplets." (PMID 25372401, 2014).
synovitis (2 papers, 2020 to 2022). Inflammation of a synovial membrane. "Since OA is usually accompanied by synovitis, the secretion of three chemokines (CXCL6, CXCL10, and CXCL16) into the culture medium by HFLS and HFLS-OA was determined." (PMID 36233118, 2022). "On the other hand, macrophages stimulated with cartilage fragments upregulated number of genes that are predominantly expressed in synovitis of OA patients such as TNF, CCL9, CXCL16, and PTGES15,16,21,26–29." (PMID 32371954, 2020).
abortion (1 paper, 2019). the ending of pregnancy by removing a fetus or embryo before it can survive outside the uterus. "The integral results of the regulatory role of CXCL16/CXCR6 axis may represent a novel therapeutic strategy to reduce the chance of recurrent spontaneous abortion or preeclampsia due to impaired decidualization." (PMID 30620718, 2019). "Therefore, we conjectured that the lower CXCL16 in pregnancy tissues could lead to the poor decidualization of endometrium, as well as spontaneous abortion." (PMID 30620718, 2019). "CXCL16 secretion and CXCR6 expression were both reduced in DSCs from patients who had undergone spontaneous abortion (aDSCs) than normal ones after 6 days of cell culture (P < 0.01)." (PMID 30620718, 2019). "The hypothesis was coinciding with the finding that CXCL16 levels were decreased in the spontaneous abortion tissues compared to pregnancy termination for nonmedical reasons." (PMID 30620718, 2019).
acute lung injury (1 paper, 2019). A condition of lung damage that is characterized by bilateral pulmonary infiltrates (pulmonary edema) rich in neutrophils, and in the absence of clinical heart failure. "Although several chemokines play key roles in the pathogenesis of acute lung injury (ALI), the roles of chemokine (C‐X‐C motif) ligand 16 (CXCL16) and its receptor C‐X‐C chemokine receptor type 6 (CXCR6) in ALI pathogenesis remain to be elucidated." (PMID 31199046, 2019).
Aden (1 paper, 2021). "Thus, high expression of CXCL16 and CXCL17 may also contribute to the formation of an immune suppressive tumor microenvironment in patients with Aden." (PMID 34459571, 2021).
Airway obstruction (1 paper, 2025). Obstruction of conducting airways of the lung. "Of note, most of the altered parameters presented here correlated negatively with the FEV1/FVC ratio, suggesting an association between the CXCL16/CXCR6 axis expression and initial airway obstruction." (PMID 40703254, 2025).
anemia (1 paper, 2016). A reduction in the number of red blood cells, the amount of hemoglobin, and/or the volume of packed red blood cells. "Besides inducing anemia, enhanced eryptosis could interfere with microcirculation, as PS-exposing erythrocytes bind to endothelial CXCL16/SR-PSO and thus adhere to the vascular wall." (PMID 26872376, 2016).